GCNT2 (glucosaminyl (N-acetyl) transferase 2 (I blood group))
Diseases named in the same sentence as GCNT2 in open-access papers (continued):
Sharing a sentence is not in itself a finding about the gene and the disease.
cancer (12 papers, 2011 to 2025). A tumor composed of atypical neoplastic, often pleomorphic cells that invade other tissues. "GCNT2 is an initiated enzyme for the synthesis of I-branched glycan which is a cancer-associated glycan." (PMID 36611197, 2023). "Loss of GCNT2 expression would lead to the ineffective I-branch conversion, thus regulating cancer progression." (PMID 36611197, 2023). "Later, emerging evidence revealed that the deregulation of GCNT2 was implicated in various cancers." (PMID 40034691, 2025). "A pan-cancer analysis was performed to define the survival implications of GCNT2 across multiple cancers including AML." (PMID 40034691, 2025). "Data from a pan-cancer analysis revealed that high-expressed GCNT2 contributed to a worse OS for AML." (PMID 40034691, 2025). "More recently, Gcnt2’s involvement in cell surface carbohydrate conversion has been investigated as a prognostic biomarker in various cancer types, where Gcnt2 expression is closely tied to cancer invasiveness." (PMID 35812759, 2022). "On the contrary, high expression of four genes, i.e., KEL, GCNT2, P1 and ERMAP, was associated with a higher cancer grade in LGG and HNSC." (PMID 35955933, 2022). "These observed differences in GCNT2 expression during malignant progression, suggest that cancers from different cell lineages transcriptionally regulate their glycosylation-related gene expression differently to uniquely control their malignant phenotype." (PMID 30135430, 2018). "The GCNT2 gene has never been linked to cancer development, so we selected NEDD9 and GABBR1 as the most promising potential candidate genes." (PMID 21283797, 2011). "In addition, by qPCR and RNA-seq we identified several cancer-related genes that regulated by AS of APEX1, which included AXIN1, GCNT2, SMAD3, CTBP2, PPARD, and FBXW11." (PMID 35780128, 2022).
infection (1 paper, 2024). The state of being infected such as from the introduction of a foreign agent such as serum, vaccine, antigenic substance or organism. "Conversely, after inhibitor infection, Hif1a (p=0.048), Fzd6 (p<0.01), and Gcnt2 (p<0.01) were increased and Atg14 (p=0.042) increased." (PMID 38770735, 2024).
GCNT2 also shares sentences with these, for which no sentence is quoted: adult T-cell lymphoma (2 papers); colorectal cancer (2); esophageal cancer (2); gastric cancer (2); metastatic melanoma (2); autosomal recessive deafness (1); beta thalassemia (1); Cohen syndrome (1); diabetes (1); endometrial carcinoma (1); hepatocellular carcinoma (1); Joubertsyndrome (1); pancreatic cancer (1); phenylketonuria (1); psychiatric disorder (1).